INS (insulin)
Diseases named in the same sentence as INS in open-access papers (continued):
Sharing a sentence is not in itself a finding about the gene and the disease.
Hyperinsulinemia (continued). "In the current study, the WD‐induced DIO with metabolic dysregulation, evidenced by increased body weight, insulin insensitivity, hyperlipidemia, and hyperinsulinemia." (PMID 35076176, 2022). "The primary aim in any patient with PCOS would be to promote weight loss through caloric deficit and physical activity, which would reduce hyperinsulinemia, increase insulin sensitivity, and often restore ovulatory cycles." (PMID 36035398, 2022). "For HMO-I, although fasting hyperinsulinemia was relieved after surgery, glucose stimulated insulin release was sharp, especially within 60 minutes after glucose stimulation, which is consistent with previous studies." (PMID 36407309, 2022). "We and others have shown that even modest differences in hyperinsulinemia can have profound consequences for insulin sensitivity, adiposity, fatty liver, longevity and cancer." (PMID 35136059, 2022). "This insulin-independent glucose disposal by E4 reduces the requirement of endogenous insulin for glucose disposal, which in turn reduces hyperinsulinemia." (PMID 36012550, 2022). "Other authors have defined fasting hyperinsulinemia as insulin levels of above 12 mU/L, while still others have suggested limits below 10 mU/L." (PMID 36160146, 2022). "Our findings indicate that minocycline can reduce hyperinsulinemia, improve insulin sensitivity, and attenuate HFD-induced increases in body mass and adiposity without altering food or water intake." (PMID 35784876, 2022). "Hyperinsulinemia leads to the antagonism between insulin and Aβ for IDE, modulating the Aβ brain clearance." (PMID 35741464, 2022). "HFD-fed WT mice developed severe fasting hyperinsulinemia, accompanied by blunt responses of insulin release to glucose injection." (PMID 35700043, 2022). "The decreased fasting insulin concentrations and enhanced prandial hyperinsulinemia after Roux-en-Y gastric-bypass (GB) surgery and sleeve gastrectomy (SG) are well documented." (PMID 35887007, 2022). "(b) The role of insulin sensitivity in postprandial glucose regulation is important to restrain hyperinsulinemia after meals." (PMID 35215472, 2022). "It has been more than 30 years since seminal clinical investigations demonstrated that individuals with arterial hypertension have reduced sensitivity to insulin and hyperinsulinemia in comparison with subjects with normal blood pressure." (PMID 36289636, 2022). "The other most used oral ADM group in our study was sulphonylureas, which induces glucose-independent insulin release from pancreatic B-cells, thus possibly leading to hyperinsulinemia." (PMID 36139140, 2022). "As suggested by its name, the hyperinsulinemic-euglycemic clamp artificially establishes a state of constant hyperinsulinemia and euglycemia to measure how effectively insulin affects glucose uptake from blood." (PMID 34887529, 2022). "It is believed that hyperinsulinemia is the main reason for increased androgen secretion because insulin acts as a co-gonadotropin on the ovary, facilitates androgen secretion from the adrenal glands, and modulates releasing of luteinizing hormone (LH)." (PMID 35457152, 2022). "IR is defined as an impaired biologic response to insulin stimulation of target tissues resulting in a compensatory increase in insulin production and hyperinsulinemia." (PMID 36466168, 2022). "The islets, on the other hand, respond to the increased insulin demand in the prediabetic, insulin-resistant state by enhanced insulin secretion and increased β-cell mass to generate compensatory hyperinsulinemia and maintain relative euglycemia." (PMID 36232419, 2022). "Insulin sensitivity in women with PCOS who develop GDM is potentially not as high as in normal glucose-tolerant women in the first trimester resulting in hyperinsulinemia to keep glucose concentrations within normal ranges." (PMID 36733795, 2022).
Hyperinsulinemia (continued). "In an attempt to compensate for the insulin inaction at the cell surface, the pancreatic β cells further increase insulin secretion, leading to hyperinsulinemia." (PMID 36555450, 2022). "Insulin-resistant individuals with compensatory hyperinsulinemia have high plasma insulin concentrations, 0.6–25 ng/ml (0.1–4.3 nM)." (PMID 34554347, 2022). "Genetic inactivation of Ptpn18 prevented HFHS induced basal hyperinsulinemia leading to improved glucose tolerance and insulin sensitivity." (PMID 35355560, 2022). "It has been demonstrated in both human and in mouse models that systemic hyperinsulinemia impairs brain insulin metabolism." (PMID 36304561, 2022). "Fourth, PI decreases skeletal muscle insulin-sensitivity, which induces hyperinsulinemia (higher levels of insulin) during and after each meal with concomitant increments in adipogenic partitioning and decrements in lipolysis." (PMID 35684086, 2022). "The scRNA-seq analysis demonstrated that hyperinsulinemia affected the immune cell composition in the PanIN microenvironment and altered cellular pathways involved in or targets of insulin signaling, such as the MAPK-ERK pathways and protein translation." (PMID 35189981, 2022). "Correlation of siMS score with hyperinsulinemia and IR (insulin, mean insulin value, HOMA-IR) proves that hyperinsulinemia and IR underlie MS." (PMID 36685849, 2022). "Our findings suggest the need for renewed focus on alternative interventions that reduce levels of insulin, inflammation, and perhaps the link between physiological stress, hyperinsulinemia, and inflammation." (PMID 36030344, 2022). "Along with basal hyperinsulinemia, chronic HF diet has been also shown to reduce glucose-stimulated insulin secretion (GSIS) despite an absolute increase in insulin release and islet insulin content." (PMID 35355560, 2022). "Low-frequency EA increases the low β-endorphin concentration, decreasing hyperinsulinemia and improving insulin sensitivity." (PMID 35822185, 2022). "This is consistent with our in vitro hyperinsulinemia model and our previous in vivo data demonstrating improved insulin sensitivity over time in mice with genetically reduced insulin production." (PMID 34921686, 2022). "On the other hand, insulin-mediated long-term depression of VTA dopamine neurons is reduced in hyperinsulinemia and aberrant insulin action in VTA–NAc pathways has been observed in insulin-resistant participants." (PMID 36170006, 2022). "The serum insulin level increased in the NC group (5.3 ± 0.7 ng/mL) compared with the Control group (0.6 ± 0.1 ng/mL) due to hyperinsulinemia, as shown in the T2D model." (PMID 35455483, 2022). "The effect of meal ingestion on insulin clearance was also examined during the fixed hyperinsulinemia induced by exogenous insulin infusion (clamp)." (PMID 35887007, 2022). "Presence of fiber along with slowly digestible starch in pulses has been linked to improved blood glucose profile, insulin sensitivity and urinary C-peptide, and tends to normalize insulin levels in individuals with hyperinsulinemia." (PMID 34585281, 2022). "IR is defined as the pathological state in which certain tissues have subnormal biological response to a given concentration of insulin, and that leads to compensatory hyperinsulinemia in order to maintain glucose blood concentrations in range." (PMID 36009471, 2022). "Correlation of siMS score with hyperinsulinemia IR (insulin basal, mean insulin value, HOMA-IR) confirmed that hyperinsulinism and IR are in the basis of MS." (PMID 36685849, 2022). "To support the relevance of our hyperinsulinemia‐induced transcriptomic changes, we compared the RNA responses in our in vitro model with two mouse skeletal muscle systems with sustained insulin signaling." (PMID 34921686, 2022).
Hyperinsulinemia (continued). "Conversely, excess inflammation in the visceral adipose tissue evoked in HF induces systemic insulin resistance, and the resulting hyperinsulinemia exacerbates HF by continuous activation of insulin signaling in cardiac tissue." (PMID 35941584, 2022). "Studies in African American women have shown that decreased hepatic insulin clearance is the main contributor to hyperinsulinemia." (PMID 35225824, 2022). "Cyclin D1 (CCND1), a downstream effector of the mitogenic insulin-signaling pathway, plays a key role in mediating the hyperinsulinemia-activated endoreplication and subsequent senescence in mature adipocytes." (PMID 35872305, 2022). "The size and DNA content of senescent cells exposed to hyperinsulinemia were significantly increased, indicating enhanced endoreplication and suggesting a mechanism by which insulin can sustain cellular stress by enhancing Cyclin D1 expression." (PMID 35872305, 2022). "The hyperinsulinemic-euglycemic clamp study is the “gold-standard” for whole body insulin sensitivity assessment; this method measures insulin-stimulated glucose disposal at a specific concentration of hyperinsulinemia." (PMID 36615744, 2022). "The presence of hyperinsulinemia is clearly responsible for MetS damage, yet despite this importance, the reference points for insulin levels are variable and often incorrect." (PMID 36160146, 2022). "In T2D, hyperinsulinemia is frequently featured because insulin target tissues are unable to perform glucose-lowering responses at normal plasma insulin levels, resulting in increased insulin secretion to compensate." (PMID 35457285, 2022). "This invariably leads to increased production of insulin (compensatory hyperinsulinemia) in the attempt to facilitate glucose uptake by target tissues, thereby preserving normal blood glucose levels." (PMID 36289636, 2022). "At baseline, participants with higher hyperinsulinemia demonstrated a specifically enhanced sugar preference which fits animal and human data on the critical role of sugar-enriched diets on whole-body insulin functioning." (PMID 36170006, 2022). "Nevertheless, for the offspring from the mHF group compared with the HF group, cross-fostering was also to relieve hyperinsulinism, accelerate insulin sensitivity and potentiate islet function in the HF-CF group." (PMID 35941695, 2022). "Conversely, the persistent congenital hyperinsulinism is due to a focal or diffuse overproduction of insulin originated by the pancreas in relation to various genetic disorders." (PMID 35135591, 2022). "Hyperinsulinism and IR in the obese are responsible for hypertension and insulin acts on the reabsorption of sodium in the kidneys, increasing the circulating level and the development of hypertension." (PMID 36685849, 2022). "Furthermore, the positive correlation that we found between the transcriptional levels of LncRNA RP11-10K16.1 and the circulating values of insulin suggested that this LncRNA could be associated with hyperinsulinism, a common condition that is observed in obese subjects." (PMID 35327332, 2022). "An elevated insulin level was highly suggestive of endogenous hyperinsulinemia, although C-peptide was within normal range." (PMID 35758364, 2022). "The decrease of hyperinsulinism observed in our study would be explained by an increased insulin catabolism and increase insulin clearance under thyroid hormone action." (PMID 35893898, 2022). "Glucose levels were unresponsive to octreotide, were more stable on diazoxide and improved with prednisone suggesting increased insulin sensitivity in addition to hyperinsulinism." (PMID 35764878, 2022). "This confirms that insulin secretion, hyperinsulinism and IR are in a mutual relationship with reduced antioxidant protection in obese patients." (PMID 36685849, 2022). "Exercise-induced hyperinsulinism (EIHI) stimulates insulin-secreting inappropriately after vigorous exercise or pyruvate injection and is featured as an autosomal dominant disease." (PMID 35742478, 2022).
Hyperinsulinemia (continued). "An orally-available selective nonpeptide SST5 agonist, CRN02481, has been shown to suppress insulin secretion and increase glucose levels in both oral glucose tolerance tests and a sulfonylurea model of hyperinsulinism." (PMID 36237195, 2022). "The appearance of hyperinsulinism, reduced insulin sensitivity and IR can precede the appearance of MS in the following years if another factor is added and therapeutic measures are not taken." (PMID 36685849, 2022). "This stimulates fetal beta cells to produce insulin (fetal hyperinsulinism) and results in a subsequent increase in fetal growth due to the anabolic effects of insulin." (PMID 35735808, 2022). "Obesity per se, with one or two risk factors (defined as pre-MS patients) and MS patients have increased insulin secretion, hyperinsulinism, IR, increased thrombotic factors PAI-1 and low antioxidant protection." (PMID 36685849, 2022). "Congenital hyperinsulinism is characterised by the inappropriate release of insulin during hypoglycaemia." (PMID 35872984, 2022). "In these two models, insulin/Akt signaling hyperactivation results, in part, from compensatory hyperinsulinemia and promotes early adaptive cardiac response and a metabolic switch from fatty acid oxidation to glycolytic way." (PMID 33682327, 2021). "It is well established that serum insulin levels correlate with SU and insulin in euglycemic hyperinsulinemia, induced by euglycemic clamp protocols, reduces renal fractional excretion of urate." (PMID 34408667, 2021). "Hyperinsulinemia also favors the cross-interaction of insulin with the IGF-1 receptor and vice versa, another route by which tumor growth can occur." (PMID 33919368, 2021). "The inability of insulin to provide normoglycemia leads to compensatory hyperinsulinemia, which further enhances insulin secretion from β-cells." (PMID 34445300, 2021). "A similar phenotype has been shown in T2DM patients with hyperinsulinemia, which is considered to be a defence mechanism to combat insulin insensitivity." (PMID 34277977, 2021). "Accordingly, vagotomy reduces glucose-stimulated insulin secretion and basal hyperinsulinemia in obese rats by reducing cholinergic action on β cells." (PMID 34192533, 2021). "The result of increased insulin levels (hyperinsulinemia) during the weight gain period of early life appears to be essential to suppress inflammation in the expanding cell population of multicellular mammals." (PMID 33744845, 2021). "Both female and male KK/HlJ groups had overt hyperinsulinemia, with between 3.8- and 4.8-fold increases in serum insulin and C-peptide levels compared to the C57BL/6 J strain, accompanied by markedly elevated HOMA-IR levels." (PMID 33711921, 2021). "Caloric restriction, increasing hepatic insulin clearance and maximizing insulin sensitivity are at present the three main strategies available for managing hyperinsulinemia." (PMID 34360563, 2021). "It has been reported, that exposition of hepatocytes to hyperinsulinemia suppresses mitochondrial production and function through the classical Akt-dependent insulin signaling pathway." (PMID 34034759, 2021). "The consequences for the endothelial function of both insulin dysfunction and hyperinsulinemia due to diabesity are more severe than the individual effects." (PMID 33995826, 2021). "Hyperinsulinemia disturbs the balance of the insulin–GH–IGF axis and this causes a shift in the insulin : GH ratio towards insulin and away from GH." (PMID 34360563, 2021). "Since hyperinsulinemia is neurotoxic, it is possible that improved insulin sensitivity after physical activity would favor neurogenesis, whereby elevated cognitive function." (PMID 33706749, 2021). "IR is characterized by an inappropriate compensatory insulin secretory response, which leads to hyperinsulinemia." (PMID 34073195, 2021). "NOS3−/− mice appeared hypertensive and presented fasting hyperinsulinemia, hyperlipidemia, and lower insulin-stimulated glucose uptake than wild-type mice." (PMID 33953784, 2021).
Hyperinsulinemia (continued). "Yet, hyperinsulinemia can be detrimental in cancer, because insulin and IGF-1 promote cancer cell growth." (PMID 33801684, 2021). "In accordance, liver-specific CEACAM1 deletion in mice leads to impaired insulin clearance, systemic hyperinsulinemia, and impaired hepatic insulin sensitivity." (PMID 33498493, 2021). "It was found that this compound reduced glucose, creatinine kinase, and alkaline phosphatase as well as cholesterol and TAG levels after application to obese, insulin-resistant mice, and mice with hyperinsulinemia." (PMID 34681728, 2021). "Alterations in insulin signaling have been reported in postmortem studies in brains from individuals with AD, as well as in patients with AD in clinical studies of plasma hyperinsulinemia and reductions in insulin levels in the CSF." (PMID 34208833, 2021). "Although the molecular actions of sphingolipids have not yet been confirmed in horses, a higher ceramide concentration is likely to decrease peripheral insulin sensitivity, leading to hyperinsulinemia instead of a normal insulin response." (PMID 34105193, 2021). "After glucose is consumed, the plasma glucose concentration modulates insulin secretion by pancreatic β cells, which creates hyperinsulinemia." (PMID 34203830, 2021). "We thus evaluated glucoregulatory capacity in RAG2−/− mice fed either diet for 6 weeks and observed a partial protection against WD-induced 5 h fasted hyperinsulinemia, insulin secretion during OGTT, body weight gain, and total fat mass." (PMID 33597537, 2021). "Ideally, quantification of plasma C-peptide and insulin levels in IDE-KO mice would help to clarify if the hyperinsulinemia seen in IDE-KO mice is related to pancreatic β-cell function or hepatic insulin clearance." (PMID 33477364, 2021). "During hyperinsulinemia (180-300 minutes), mean glucose was successfully maintained at physiological concentration (lean placebo 5.32 ± 0.17 vs lean insulin 4.90 ± 0.13 vs obese placebo 5.25 ± 0.14 vs obese insulin 4.92 ± 0.26 mmol/L)." (PMID 33270115, 2021). "Our findings suggested an intact pancreatic function in the AAVshFNDC4 treated group and argued for an increased peripheral insulin resistance resulting in hyperinsulinemia compared to the AAVshControl treated group." (PMID 34016966, 2021). "Western blot analysis showed increased phosphorylation level of protein kinase B (AKT) after acute insulin stimulation, which was lost in AV under hyperinsulinemia, indicating acquired insulin resistance of the AV tissue in response to elevated insulin levels." (PMID 34203572, 2021). "Due to decreased enzyme production, insulin secretion is released from the inhibitory effect of digestive enzymes that leads to hyperinsulinemia." (PMID 34566890, 2021). "Many studies have reported that adiponectin enhances insulin activity, and hyperinsulinemia was already described as a possible mechanism of high BMD in CGL." (PMID 34574647, 2021). "The prevalence of hyperinsulinemia (insulin ≥ 15 mU/mL) in the total sample was 6.52% (95% CI 4.35–9.65), being 8.41% (95% CI 4.54–15.09) and 5.87% (95% CI 3.49–9.72), in PVh and PoA, respectively—data not shown in the table." (PMID 34666809, 2021). "Second, metformin inhibits hepatic gluconeogenesis and stimulates peripheral insulin sensitivity, thus inhibiting the tumour-specific stimulatory effects of hyperinsulinemia." (PMID 33927955, 2021). "Hyperinsulinemia should thus be considered an indication for preventive measures intended to reduce plasma insulin levels, increase tissue insulin sensitivity, and lessen the risk of laminitis." (PMID 33915682, 2021). "In rodents, for example, bisphenol, an endocrine-disrupting chemical, increases pancreatic insulin content and favors postprandial hyperinsulinemia." (PMID 34360563, 2021). "Insulin and hyperinsulinemia reduce renal fractional excretion of urate (FeU) and play a key role in the genesis of hyperuricemia and gout, via uncharacterized mechanisms." (PMID 34408667, 2021).